INS (insulin)
Diseases named in the same sentence as INS in open-access papers (continued):
Sharing a sentence is not in itself a finding about the gene and the disease.
Impaired glucose tolerance (continued). "Earlier studies also suggested that D-chiro-inositol (DCI) supplementation could lower serum insulin and enhance insulin sensitivity in PCOS patients with impaired glucose tolerance, thus improving ovulatory function." (PMID 40008316, 2025). "These patients have impaired glucose tolerance and impaired glucose-induced insulin secretion." (PMID 40422193, 2025). "This relationship may be mediated by excessive cholesterol accumulation in β-cells, leading to dysfunction, impaired glucose tolerance, and reduced insulin secretion." (PMID 41341134, 2025). "In humans, chromium supports insulin production and blood sugar control; reduces the heart rate in people with impaired glucose tolerance; reduces inflammation; is involved in weight and free-testosterone regulation in patients with polycystic ovary syndrome; and normalizes appetite." (PMID 40509103, 2025). "Similarly, a 12-week RCT in patients with impaired glucose tolerance showed improvements in fasting glucose levels, insulin sensitivity, lipid profiles, and anthropometric markers after high-dose chlorogenic acid supplementation." (PMID 40565007, 2025). "In a female rat model of polycystic ovary syndrome with impaired glucose tolerance and elevated plasma insulin, EPO treatment improved glucose tolerance, decreased serum insulin levels, and reduced disease-associated reproductive manifestations, although to a lesser extent than metformin." (PMID 39996752, 2025). "Twenty-four patients with impaired glucose tolerance (20 females and 4 males) participated in a randomized, double-masked, placebo-controlled study to evaluate the outcome of A. dracunculus on insulin secretion, insulin sensitivity, and glycemic control." (PMID 39941696, 2025). "Our study revealed that, under ad libitum feeding conditions, AO rats are obese, exhibit impaired glucose tolerance and reduced insulin sensitivity, whereas systemic triglyceride levels are higher and the levels of total cholesterol, HDL and LDL cholesterol are lower, when compared to DA rats." (PMID 40427746, 2025). "Interestingly, under normal diet feeding, impaired glucose tolerance and insulin sensitivity were observed in PCE offspring rats at PW36, and noticeable IR was observed starting from PW40." (PMID 40903796, 2025). "Alternatively, given the reduced insulin sensitivity, hyperinsulinaemia and impaired glucose tolerance of pregnant HFHSD mice it is possible that elevated post‐prandial glucose might also contribute to reduced GVA mechanosensitivity." (PMID 40023799, 2025). "The higher incidence of GDM among older women could be attributed to progressive vascular endothelial damage in older ages, impaired glucose tolerance, reduction in insulin sensitivity, and pancreatic β-cell dysfunction as maternal age increases." (PMID 40964160, 2025). "An oral glucose tolerance test (OGTT) revealed fasting blood glucose of 3.41 mmol/L, insulin of 10.07 μIU/mL, and C-peptide of 0.81 ng/mL; 2-hour postprandial values were 12.08 mmol/L for glucose, 28.98 μIU/mL for insulin, and 1.53 ng/mL for C-peptide, consistent with impaired glucose tolerance." (PMID 41367853, 2025). "While hyperthyroidism may initially improve insulin sensitivity, prolonged hyperthyroid states have been shown to lead to pancreatic β-cell exhaustion with reduced insulin secretion and impaired glucose tolerance." (PMID 39831884, 2025). "To test whether the impaired glucose tolerance observed in myeloid Gq is due to changes in insulin secretion, we evaluated β-cell response to different insulin secretagogues under RC and HFD conditions." (PMID 41278909, 2025). "These cumulative changes ultimately may lead to altered systemic metabolism and adiposity in vivo, with impaired glucose tolerance and insulin sensitivity and increased adiposity observed in LL:AA mice over time." (PMID 41004571, 2025).
Impaired glucose tolerance (continued). "These biochemical findings parallel our results and suggest that hypovitaminosis D may contribute to impaired glucose tolerance through pathways involving pancreatic beta-cell function and insulin sensitivity." (PMID 41293367, 2025). "In conclusion, the absence of HNF4α leads to impaired glucose tolerance and loss of insulin-producing beta cells, influenced by sex and age." (PMID 41017587, 2025). "FXR knockout mice show impaired glucose tolerance and reduced insulin sensitivity, suggesting that BA activation of FXR may improve IR by inhibiting hepatic SREBP-1c expression and/or modulating glucose-induced lipogenesis." (PMID 40177494, 2025). "Notably, one patient with impaired glucose tolerance achieved normoglycemia, while the others exhibited partial restoration of insulin secretion." (PMID 40842499, 2025). "In this study, zebrafish exposed to a high-glucose treatment for 8 weeks exhibited symptoms related to T2DM, including impaired glucose tolerance and a significant decrease in skeletal muscle insulin levels (since the blood volume of zebrafish is too small to detect serum insulin levels)." (PMID 39859466, 2025). "Interestingly, KCNH6-βKO mice exhibited impaired glucose tolerance and lower serum insulin concentrations after glucose loading which was different from those of KCNH6 GKO mice." (PMID 38349432, 2024). "Interestingly, the diet-induced prediabetic state with both impaired glucose tolerance and insulin sensitivity as well as massive ectopic lipid deposition did not affect cardiac function prior induction of MI." (PMID 40604298, 2024). "Furthermore, 23.5% of the teenagers had impaired glucose tolerance, 11% had elevated serum testosterone levels, and 8.6% had increased fasting insulin levels." (PMID 38711716, 2024). "However, we found that KCNH6-βKO mice exhibited severe phenotype of impaired glucose tolerance and insulin secretion even at 8 weeks age which was different from those of KCNH6 GKO mice." (PMID 38349432, 2024). "Research suggests that selenoprotein P (SELENOP) produced by the liver can transport selenium to peripheral tissues, and that elevated serum SELENOP levels may result in decreased insulin sensitivity and impaired glucose tolerance." (PMID 39149550, 2024). "High OPG levels are associated with impaired glucose tolerance (IGT) which could be as a result of insulin levels decreasing in patients with IGT and the similar roles between OPG and insulin in blocking osteoclastogenesis." (PMID 39588310, 2024). "Wild-type mice at 16 months of age showed higher glycemia, much higher insulin levels than 5-month-old wild-type mice, impaired glucose tolerance and reduced insulin sensitivity in the insulin tolerance test, indicating the appearance of insulin resistance with aging." (PMID 37914970, 2024). "Impaired glucose tolerance may lead to increased circulatory insulin levels in an attempt to ensure optimal gluco-lipid regulation." (PMID 39545041, 2024). "Therefore, FXR−/− mice fed with HFD displayed reduced plasma insulin levels and impaired glucose tolerance compared with the control FXR+/+ HFD group." (PMID 39702527, 2024). "In our data, the reduced correlation between insulin secretion and insulin content specifically in animals with impaired glucose tolerance may be indicative of beta-cell dysfunction at the level of the insulin secretory pathway uncoupling these variables." (PMID 38568150, 2024). "However, fasting and postprandial blood-glucose levels are increased, leading to impaired glucose tolerance and chronic hyperglycemia (the diabetic condition) when insulin secretion capacity is relatively reduced." (PMID 40607157, 2024).
Impaired glucose tolerance (continued). "The levels of IL-6 were higher in the low dose of PN which may contribute to the insulin-resistant state and impaired glucose tolerance, while IL-6 levels were lower in the high dose of PN and metformin-treated mice." (PMID 37426418, 2023). "GTT and ITT showed impaired glucose tolerance and impaired insulin sensitivity." (PMID 37884540, 2023). "Previous studies showed that FSH/FSHR mediated the increased fat mass and fat redistribution in postmenopausal women, which may contribute to induce impaired glucose tolerance, indirectly, by decreased insulin sensitivity." (PMID 37914684, 2023). "However, previous research has indicated that the accumulation of excess cholesterol can lead to β-cell dysfunction, resulting in impaired glucose tolerance and compromised insulin secretion." (PMID 38105214, 2023). "This viewpoint may also imply that the compensatory metabolic features of the β-cells in response to age-dependent development are impaired glucose tolerance, decreased insulin sensitivity, and elevated IR." (PMID 36834922, 2023). "The majority of people have type‐2 DM, caused by a reduction in the response to insulin thereby reducing its ability to control target cell metabolism, which triggers an increase in insulin production leading to pancreatic damage through exhaustion, and impaired glucose tolerance." (PMID 37649224, 2023). "We conducted an insulin tolerance test to determine whether the impaired glucose tolerance in the knockout than wildtype mice was due to reduced sensitivity to insulin." (PMID 36979650, 2023). "It has also been reported that the silencing of the lncRNA MEG3 resulted in impaired glucose tolerance, decreased insulin secretion, and fewer insulin-positive cells, indicating that MEG3 may be a novel β cells regulator." (PMID 37108143, 2023). "We aimed to develop a novel blood-based proteomic signature to reliably estimate a direct measure of insulin sensitivity in men and women with normoglycaemia or impaired glucose tolerance using a high-throughput platform able to measure reliably hundreds of low-abundance proteins in plasma." (PMID 37329449, 2023). "Hence, CSF1R inhibition by PLX5622 led to a discordant behaviour of impaired glucose tolerance but improved insulin sensitivity." (PMID 37792013, 2023). "Additionally, it is now well understood that a decrease in acute insulin response, a marker of change in the first phase of insulin release, constitutes the initial indicator of impaired glucose tolerance." (PMID 37144278, 2023). "Moreover, impaired glucose tolerance and insulin sensitivity in db/db mice were improved by melatonin." (PMID 37488285, 2023). "One of these subjects developed impaired glucose tolerance and is on insulin." (PMID 36814577, 2023). "Metabolic phenotyping revealed impaired glucose tolerance following M5 tanycyte ablation coupled with longtime (>20 weeks) high fat diet feeding, as well as increased insulin sensitivity and reduced insulin concentrations after 18 weeks, despite unchanged body weight and fat mass." (PMID 36949050, 2023). "This may be because decreased insulin sensitivity and impaired glucose tolerance occur before the rise in BAs." (PMID 38027178, 2023). "On the contrary, the low dose of PN-treated mice increased the gene expression of Pck-1, which might be due to the low dose of PN-treated mice having impaired glucose tolerance and developing an insulin-resistant state." (PMID 37426418, 2023). "Similarly, chronic administration of vitamin C and E to normo-glycemic, healthy rats impaired glucose tolerance and insulin sensitivity, effects that were well-correlated with an increase in hepatic GSH in these animals." (PMID 37237860, 2023). "Our data demonstrated body weight gain, increased renal mass and reduced insulin sensitivity with impaired glucose tolerance in PCOS animals, which validated the metabolic features of PCOS, as earlier reported that women with PCOS manifest metabolic abnormalities." (PMID 37789355, 2023).
Impaired glucose tolerance (continued). "In accordance with this remarkable resistance to impaired glucose tolerance, the insulin tolerance test (ITT) showed that compared with WT HF mice, Fat-1 HF mice elicited a significant improvement in insulin sensitivity and remained comparable to Ctrl diet-fed mice." (PMID 36234919, 2022). "Interestingly, IGHD patients also had low insulin levels and relatively low IR, though their β-cell function was reduced and their frequency of impaired glucose tolerance was increased." (PMID 35525976, 2022). "However, many studies stated that ghrelin inhibited insulin secretion both in humans and in animals and was accompanied by increased glucose levels and impaired glucose tolerance." (PMID 35525976, 2022). "Additionally, NCD Vsig4−/− recipient mice treated with obese mEVs had significantly lower levels of insulin secretion in response to glucose injection and impaired glucose tolerance." (PMID 35091566, 2022). "Moreover, Romboutsia species, included as an additive in the diet of mice, showed impaired glucose tolerance and fasting insulin compared with mice fed with standard diet, both parameters associated with increments in body weight." (PMID 35163595, 2022). "In both cases, it might be mediated by HIF-1α and based on impaired glucose tolerance, increased insulin secretion, alteration in B-cell function, and the influence of metabolic enzymes such as acetyl-coenzyme A." (PMID 35054894, 2022). "Insulin-stimulated muscle glucose uptake is substantially (>50%) reduced among individuals with impaired glucose tolerance and T2D This supports an important hypothesis that a defect in muscle insulin action is found in those with T2D." (PMID 36490255, 2022). "Often, NNT deficiency due to a spontaneous missense mutation of Nnt in B6J mice is considered to be responsible for these phenotypic differences and abnormal traits in B6J mice, including metabolic dysfunctions such as impaired glucose tolerance, diminished insulin secretion, and overweightness." (PMID 36548271, 2022). "In late pregnancy, due to the continuous increase of anti-insulin hormone secretion, insufficient insulin compensatory secretion or decreased insulin sensitivity results in abnormal glucose metabolism, resulting in impaired glucose tolerance during pregnancy (GIGT) or gestational diabetes." (PMID 36093497, 2022). "Excluding a vast number of GOMs for type 1 diabetes mellitus, where information on exogenous insulin administration can be used duringmodel identification, a comparatively small number of GOMs applied to subjects withnormal and impaired glucose tolerance has been published." (PMID 34225468, 2022). "We previously reported that transgenic overexpression of TAP–14-3-3ζ in mice was associated with defective insulin secretion in vivo, along with impaired glucose tolerance, but it was not clear if this decrease GSIS was islet specific." (PMID 35298439, 2022). "The development of hepatosteatosis could at least in part explain the impaired glucose tolerance in ActRIIB-Fc-treated mice due to reduced hepatic insulin sensitivity." (PMID 35024891, 2022). "Similarly, treatment with valsartan is able to improve IR and increase glucose-stimulated insulin secretion in patients with impaired fasting glucose or impaired glucose tolerance." (PMID 36034421, 2022). "Furthermore, lower insulin sensitivity and impaired glucose tolerance were also observed in their unaffected siblings compared with the controls." (PMID 35806096, 2022). "Furthermore, HFD-fed Xaf1 Tg mice demonstrated increased β-cell apoptosis, lowered insulin expression, and impaired glucose tolerance compared with WT mice fed the same diet." (PMID 35829914, 2022). "Furthermore, HFD-fed Xaf1 Tg mice demonstrated increased β-cell apoptosis, attenuated insulin expression, and impaired glucose tolerance compared with WT mice fed the same diet." (PMID 35829914, 2022).
Impaired glucose tolerance (continued). "Up to a point, insulin sensitivity impairment is compensated for by an increase in insulin production by pancreatic beta cells, but in women with impaired glucose tolerance, this mechanism is insufficient to protect against the development of further disturbances in carbohydrate metabolism." (PMID 36296986, 2022). "Impairments in insulin secretion and insulin sensitivity may result in impaired glucose tolerance, leading to T2DM." (PMID 35893259, 2022). "Finally, impaired glucose tolerance and insulin sensitivity (based on ipITT) confirmed impairments in peripheral glucose homeostasis." (PMID 35103058, 2022). "Likewise, our data confirmed that the offspring of mice with HFD mothers presented impaired glucose tolerance, insulin sensitivity and insulin secretion, which was consistent with the previous animal study." (PMID 35941695, 2022). "Overall, given the importance of insulin in the metabolism of these amino acids, it is very likely that small alterations in insulin sensitivity are responsible for a reduction in their catabolism long before the onset of impaired glucose tolerance." (PMID 36615726, 2022). "Furthermore, maternal stress impaired glucose tolerance, and significantly increased basal plasma corticosterone and insulin levels as well as HOMA-IR index, however, decreased ISI Matsuda." (PMID 35869151, 2022). "In addition, Lit/lit mice (whose gene encoding the GH releasing hormone-receptor is mutated), GH knockout (GHKO) mice, and GH receptor knockout (GHRKO) mice all had decreased insulin levels, increased IS and impaired glucose tolerance." (PMID 35525976, 2022). "It has also been shown that glucose-stimulated insulin secretion linearly decreases with age at a rate of 0.7% per year (7% per decade) in subjects with normal glucose tolerance, while it doubles in subjects with impaired glucose tolerance." (PMID 34206854, 2021). "However, short-term dosing research has suggested that antipsychotic medication involves weakened insulin sensitivity and impaired glucose tolerance." (PMID 34690937, 2021). "Low testosterone concentrations are correlated with an increased fat mass (particularly central adiposity), reduced insulin sensitivity, impaired glucose tolerance, elevated triglycerides and cholesterol and low HDL-cholesterol, contributing to cardiovascular risk." (PMID 33546773, 2021). "The oral glucose tolerance test (OGTT) and insulin tolerance test showed impaired glucose tolerance with decreased insulin sensitivity in both the SO and Lard groups, although the glucose tolerance was significantly worse in the SO group, along with more elevated plasma insulin levels." (PMID 33997711, 2021). "Moreover, the levels of plasma RBP4 are significantly elevated in HUA rats and patients with HUA, which is accompanied by impaired glucose tolerance and reduced insulin sensitivity in HUA rats." (PMID 34177800, 2021). "However, when IR continues, β cells gradually fail to secrete adequate amounts of insulin for metabolic compensation, leading to insulin insufficiency and impaired glucose tolerance." (PMID 34069388, 2021). "Furthermore, mice developed impaired glucose tolerance and decreased insulin sensitivity at four months postpartum." (PMID 33467592, 2021). "Furthermore, this stress induced hyperglycaemic state resulted in impaired glucose tolerance and reduced insulin sensitivity." (PMID 33805856, 2021). "Treatment with ZBPYR could improve the impaired glucose tolerance and insulin sensitivity of DM mice." (PMID 33603781, 2021). "Several studies have reported that fluoride can be toxic to the reproductive system causing decreased fertility Recently, reports have indicated fluoride toxicity during immune and inflammatory responses and impaired glucose tolerance with insulin resistance in peripheral tissues." (PMID 33513857, 2021). "Visceral obesity is an independent predictor of insulin sensitivity and impaired glucose tolerance." (PMID 34769623, 2021).